MIR27B (microRNA 27b)
Synonyms: hsa-mir-27b; MIR-27b; MIRN27B; miRNA27B
Gene: MicroRNA gene on chromosome 9 (95,085,445 to 95,085,541, forward strand). Ensembl gene ENSG00000207864.
Pathways (Reactome):
Signal Transduction: TGFBR3 expression
Gene Ontology:
Cellular component: RISC complex
Homologues: Orthologues: chimpanzee ptr-mir-27b (100% identical), macaque MIR27B (95% identical), tropical clawed frog xtr-mir-27b (92% identical), pig MIR27B (90% identical), dog MIR27B (82% identical), guinea pig MIR27B (75% identical), mouse Mir27b (75% identical), zebrafish mir27d (68% identical). Paralogues in human: MIR27A (53% identical).
Diseases named in the same sentence as MIR27B in open-access papers:
MIR27B is named in the same sentence as 1 disease in open-access papers, as found by Europe PMC text mining. Sharing a sentence is not in itself a finding about the gene and the disease. The quoted sentences say what the papers report.
tumor (1 paper, 2021). "MIR27B is a well-validated tumor suppressor and mechanistically modulates critical oncogenic molecules such as the nuclear receptor subfamily 5 group A member 2 gene (NR5A2) and response element-binding protein (CREB1)." (PMID 33920789, 2021). "Similarly, MIR27B mRNA binds with the 3′-UTR of the CREB1 gene, which blocks estrogen-induced transcription due to lack of inducer transcripts for DNA binding protein suppressing tumor proliferation." (PMID 33920789, 2021).